SEC61A1 (SEC61 translocon subunit alpha 1)
Description:
Component of SEC61 channel-forming translocon complex that mediates transport of signal peptide-containing precursor polypeptides across the endoplasmic reticulum (ER). Forms a ribosome receptor and a gated pore in the ER membrane, both functions required for cotranslational translocation of nascent polypeptides. May cooperate with auxiliary protein SEC62, SEC63 and HSPA5/BiP to enable post-translational transport of small presecretory proteins. The SEC61 channel is also involved in ER membrane insertion of transmembrane proteins: it mediates membrane insertion of the first few transmembrane segments of proteins, while insertion of subsequent transmembrane regions of multi-pass membrane proteins is mediated by the multi-pass translocon (MPT) complex. The SEC61 channel cooperates with the translocating protein TRAM1 to import nascent proteins into the ER. Controls the passive efflux of calcium ions from the ER lumen to the cytosol through SEC61 channel, contributing to the maintenance of cellular calcium homeostasis. Plays a critical role in nephrogenesis, specifically at pronephros stage (By similarity).
Synonyms: SEC61A; ADTKD5; CVID15; HNFJ4; HSEC61; SEC61
Tractability: Small molecule: a structure with a bound ligand is known. Antibody: UniProt predicts a signal peptide or a membrane-spanning region. PROTAC: ubiquitination databases record sites on it; its protein half-life has been measured.
Chemical probes: Cotransin
Gene: Protein-coding gene on chromosome 3 (128,051,641 to 128,071,705, forward strand). Ensembl gene ENSG00000058262.
Subcellular location: Endoplasmic reticulum membrane
Subcellular location (Human Protein Atlas): Endoplasmic reticulum
Pathways (Reactome):
Immune System: ER-Phagosome pathway
Metabolism of proteins: SRP-dependent cotranslational protein targeting to membrane
Gene Ontology:
Molecular function: calcium channel activity; protein binding; ribosome binding; protein transmembrane transporter activity; signal sequence binding
Biological process: cotranslational protein targeting to membrane; endoplasmic reticulum organization; post-translational protein targeting to endoplasmic reticulum membrane; post-translational protein targeting to membrane, translocation; protein insertion into ER membrane; SRP-dependent cotranslational protein targeting to membrane; SRP-dependent cotranslational protein targeting to membrane, translocation; pronephric nephron development; protein targeting to ER; calcium ion transmembrane transport; protein transport; response to type II interferon
Cellular component: endoplasmic reticulum; endoplasmic reticulum membrane; membrane; Sec61 translocon complex
Genetic constraint (gnomAD): Loss-of-function variants: 13 observed, 51.15 expected, observed/expected ratio (o/e) 0.25, 90% interval 0.16 to 0.4. The upper end of that interval is the gene's LOEUF score, 0.4, which puts it in group 1 of 6, group 1 being the genes least tolerant of losing a copy. Missense variants: 281 observed, 618.17 expected, observed/expected ratio (o/e) 0.45, 90% interval 0.41 to 0.5. Synonymous variants: 246 observed, 240.6 expected, observed/expected ratio (o/e) 1.02, 90% interval 0.92 to 1.14.
Gene-disease validity (ClinGen):
ClinGen rates the evidence that SEC61A1 causes each of these diseases.
SEC61A1 deficiency (autosomal dominant): Moderate. Any Mendelian disease in which the cause of the disease is a mutation in the SEC61A1 gene.
Homologues: Orthologues: guinea pig SEC61A1 (100% identical), macaque SEC61A1 (100% identical), mouse Sec61a1 (100% identical), pig SEC61A1 (100% identical), rat Sec61a1 (100% identical), chimpanzee SEC61A1 (99% identical), rabbit SEC61A1 (99% identical), tropical clawed frog sec61a1 (98% identical), zebrafish sec61a1a (97% identical), zebrafish sec61a1b (96% identical), dog SEC61A1 (95% identical), Drosophila melanogaster Sec61alpha (89% identical), and 1 more. Paralogues in human: SEC61A2 (93% identical).
Diseases named in the same sentence as SEC61A1 in open-access papers:
SEC61A1 is named in the same sentence as 61 diseases in open-access papers, as found by Europe PMC text mining. Sharing a sentence is not in itself a finding about the gene and the disease. The quoted sentences say what the papers report.
diabetes (8 papers, 2015 to 2025). "Finally, six genes (Sec61a1, Insr, Sirt1, Pdpk1, Sin3a, and Sqstm1) were predicted to be associated with diabetes and obesity." (PMID 32257911, 2019). "Thereby, transgenic ß-cell-specific expression of normal SEC61A1 could rescue diabetes and ß-cell loss in mutant mice proving a critical role of Sec61α1 in the ß-cell response to glucose." (PMID 29263911, 2017). "In addition, a mutation in the Sec61a1 gene (p.Tyr344His) results in excessive ER stress and apoptosis of pancreatic β cells in C57BL/6 mice, resulting in diabetes and hepatosteatosis." (PMID 34692675, 2021). "Another mutation of the SEC61A1 gene (Y344H) was found to cause excessive ER stress and, as a consequence, inducing apoptosis of pancreatic ß-cells in C57BL/6 mice, which finally led to diabetes and hepatosteatosis." (PMID 29263911, 2017).
multiple myeloma (5 papers, 2017 to 2023). "Furthermore, the mutation of SEC61A1 in multiple myeloma cell lines results in UPR activation and cell death." (PMID 36860866, 2023). "Hsa_circ_0007841 transcripted by SEC61A1 was found to be involved in drug resistance in doxorubicin and bortezomib-treated multiple myeloma patients." (PMID 36293493, 2022). "SEC61A1 is a downstream XBP1 target gene, downregulated upon inhibition of XBP1 splicing with MKC-3946 treatment in multiple myeloma cells." (PMID 32878211, 2020).
colon adenocarcinoma (3 papers, 2021). "SEC61 translocon alpha 1 subunit (SEC61A1) was previously reported to contribute to progression of colon adenocarcinoma via the MNX1-AS1-miR-218-5p-SEC61A1 network." (PMID 33627127, 2021). "In addition, MNX1-AS1 and ELFN1-AS1 were found to facilitate cell proliferation through regulating miR-218-5p/SEC61A1 axis in colon adenocarcinoma." (PMID 33845844, 2021).
common variable immunodeficiency (3 papers, 2022 to 2024). "The diseases include SEC61A1-linked common variable immunodeficiency, neutropenia and tubulointerstitial kidney disease, SEC61B- and SEC63-linked polycystic liver disease, and TRAP-, as well as TRC35-, TRC40-, and CAML-linked congenital disorders of glycosylation." (PMID 37762469, 2023).
lung carcinoma (3 papers, 2013 to 2022). "With a relatively loose threshold (p < .2), the genes Dhx16, Upf2, Denr, Notch3, Dyrk2, Sec61a1, Hmmr, and Noa1 were reversed in at least three treatment protocols and most of these genes were reported to be related to COPD or lung cancer." (PMID 35993327, 2022).
neutropenia (3 papers, 2020 to 2023). A decrease in the number of neutrophils found in the blood. "In this region, several candidate genes (GATA2, PPARG, RAF1 and SEC61A1) associated with functions such as quantity of leukocytes or neutropenia were identified." (PMID 33116177, 2020).
viral infection (3 papers, 2022 to 2025). "Because we were unable to express the full length Sec61A1 protein in our rescue studies, we focused on characterizing the role of Loqs in viral infection in more detail." (PMID 35482886, 2022).
antibody deficiency (2 papers, 2019 to 2023). "Similarly, perturbation of the ER compartment can result in PIDs, as highlighted by the primary antibody deficiency due to plasma cell defects observed in patients with mutations in the Sec61 translocon subunit SEC61A1." (PMID 30237509, 2019).
Autosomal dominant tubulointerstitial kidney disease (2 papers, 2017 to 2019). "It shares some common features with autosomal dominant tubulointerstitial kidney diseases caused by mutations in MUC1 (mucin 1, 1q21), HNF1B (HNF1beta, 17q12), REN (renin, 1q32) and SEC61A1 (Sec 61 translocon alpha 1 subunit, 3q21)." (PMID 28437467, 2017).
autosomal-dominant tubulo-interstitial kidney disease (2 papers, 2017 to 2022). "This was similar to the depletion observed when expressing in the same cells SEC61A1-V67G or SEC61A1-T185A, two heterozygous missense mutations already shown to result in autosomal-dominant tubulo-interstitial kidney disease (ADTKD)." (PMID 36277220, 2022).
congenital neutropenia (2 papers, 2022 to 2025). "In a recent study, the point mutation Q92R in SEC61A1 was identified in a patient with severe congenital neutropenia." (PMID 36277220, 2022). "In severe congenital neutropenia (SCN), mutations such as ELANE p.Ala79del (c.234_236del) and p.Val197GlufsTer18 (c.589_590insAGGCCGGC) disrupt neutrophil elastase function, while a de novo SEC61A1 missense mutation (c.A275G; p.Q92R) further expands the genetic heterogeneity of SCN." (PMID 41141324, 2025).
dengue (2 papers, 2022 to 2023). "Depletion analysis demonstrated that both Sec61A1 and Loqs have pro-viral functions in the dengue viral infectious cycle." (PMID 35482886, 2022). "Using a novel RNA-protein detection assay, the interactions of Sec61A1 and Loqs with the dengue viral genome were found to have pro-viral functions in infected mosquito cells." (PMID 35482886, 2022).
hepatocellular carcinoma (2 papers, 2022). A malignant tumor that arises from hepatocytes. "SEC61A1 was reported to play a role in colon and hepatocellular cancer progression." (PMID 36293493, 2022).
acute myeloid leukemia (1 paper, 2024). Acute myeloid leukemia (AML) is a group of neoplasms arising from precursor cells committed to the myeloid cell-line differentiation. "The malfunction of SEC61A1 has been linked to several types of cancers, but its role in acute myeloid leukemia (AML) remains poorly understood." (PMID 38584833, 2024).
asthma (1 paper, 2022). "We found PDCD11 was negatively associated with asthma-related TFs, including WT1, ZEB1, and RERE; ALDH18A1 was negatively associated with WT1 and RERE; SEC61A1 was negatively related with WT1 and ZEB1." (PMID 35169275, 2022). "Hence, PDCD11, ALDH18A1, and SEC61A1 may play a role in the development of asthma through transcriptional regulation-related mechanisms." (PMID 35169275, 2022).
breast carcinoma (1 paper, 2022). "Here, we found four upregulated hub genes (RPSA, SEC61A1, ITGB1, PSMB5) and three downregulated hub genes (PSME3, SNRNP70, SRSF3) that are significantly associated with poor overall survival of breast cancer patients." (PMID 36293493, 2022).
colon cancer (1 paper, 2023). "Additionally, high expression of UBA1 and SEC61A1 were associated with a poorer prognosis in colon cancer patients." (PMID 37417208, 2023).
fungal infections (1 paper, 2024). "Although, evidence suggests cross‐presentation including MHC class I molecules can occur in fungal infections, and one of the genes (SEC61A1) we found to be differentially expressed is associated with antigen cross‐presentation." (PMID 39310794, 2024).
glioma (1 paper, 2025). A benign or malignant brain and spinal cord tumor that arises from glial cells (astrocytes, oligodendrocytes, ependymal cells). "Here, we identified a novel ER stress and UPR-driven gene signature, ESURATAG, composed of six genes (DERL2, RPN2, SEC13, SEC61A1, SEC61B, and STT3A) that are significantly upregulated in gliomas from older patients and strongly linked to tumor aggressiveness." (PMID 40718795, 2025). "Six out of eight genes namely, DERL2, RPN2, SEC13, SEC61A1, SEC61B and STT3A were interacting, and were combined into ER stress and UPR-driven aging-related tumor aggressiveness in glioma (ESURATAG) gene signature." (PMID 40718795, 2025). "We identified ER stress and UPR as key aging-related mechanism behind tumor aggressiveness in gliomas, and developed a six gene “ER Stress and UPR-driven Aging-related Tumor Aggressiveness in Glioma” (ESURATAG) gene signature, comprising DERL2, RPN2, SEC13, SEC61A1, SEC61B, and STT3A." (PMID 40718795, 2025).
liver cancer (1 paper, 2024). An epithelial or non-epithelial malignant neoplasm that arises from the liver. "Upregulation of HSPA8 and SEC61A1 affected hepatocarcinogenesis, identifying HSPA8 and SEC61A1 as potential therapeutic targets in liver cancer." (PMID 39593796, 2024).
myelogenous leukemia (1 paper, 2024). "The suppression of SEC61A1 and SEC61B has been observed to stimulate Ddit3 expression in myelogenous leukemia cells." (PMID 39000233, 2024).
Peri-Implantitis (1 paper, 2019). An inflammatory process with loss of supporting bone in the tissues surrounding functioning DENTAL IMPLANTS. "Three leader genes (PSMD10, SOS1, WASF3), eight cross-talk genes (PSMD10, PSMD6, EIF2S1, GSTP1, DNAJC3, SEC61A1, MAPT, and NME1), and one signaling pathway (IL-17 signaling) emerged as peri-implantitis and T2DM linkage mechanisms." (PMID 31275749, 2019). "The possible mechanisms of SEC61A1 (Sec61 Translocon Alpha 1 Subunit) in T2DM and peri-implantitis appear to be similar to those of the DNAJC3 gene." (PMID 31275749, 2019).
type 2 diabetes (1 paper, 2022). "These mutations result in various clinical phenotypes, including type 2 diabetes mellitus (T2D), immunodeficiency, tubulo-interstitial kidney disease and neutropenia (for mutations in SEC61A1)." (PMID 36277220, 2022).
cancer (18 papers, 2014 to 2025). A tumor composed of atypical neoplastic, often pleomorphic cells that invade other tissues. "The aberrant function of the SEC61A1 protein has been implicated in various human cancers, including head, lung, prostate, and glioblastoma, and has been targeted as a therapeutic option in multiple myeloma." (PMID 38584833, 2024). "Yeast RFT1 is homologous to human RFT1 and SEC61A1 and has been used to study congenital disorder of glycosylation type I and cancer." (PMID 40512775, 2025). "The results of previous studies have confirmed that SLC41A3, SEC61A1, LRP4, PPM1G, and HSP90AA1 play important roles in cancer progression." (PMID 35799605, 2022).
tumor (10 papers, 2017 to 2025). "Similarly, in this study, we determined that miR-491-5p exerted tumor-suppressive functions in HCC through targeting SEC61A1." (PMID 33627127, 2021).
hematological malignancies (1 paper, 2024). "We found that high expression of SEC61A1 was associated with upregulation of EPHA3, MMP7, BIRC7, and ROS1, all of which have been reported as prognostic markers or therapeutic targets in hematological malignancies." (PMID 38584833, 2024). "Previous studies have indicated that targeting SEC61A1 enhances sensitivity to anticancer drugs in various hematological malignancies." (PMID 38584833, 2024).
SEC61A1 also shares sentences with these, for which no sentence is quoted: channelopathies (7 papers); infection (6); Buruli Ulcer (4); influenza (2); amyotrophic lateral sclerosis (1); chronic kidney disease (1); colorectal cancer (1); congenital disorder of glycosylation (1); COVID-19 (1); dilated cardiomyopathy (1); escherichia coli infection (1); esophageal cancer (1); fibrosis (1); gastric cancer (1); genetic diseases (1); glioblastoma (1); Hypoglycemia (1); ischaemia (1); ischemia reperfusion injury (1); ischemic cardiomyopathy (1); Kidney Disease (1); myocardial infarction (1); nasopharyngeal carcinoma (1); Obesity (1); osteosarcoma (1); pneumonia (1); polycystic liver disease (1); prostate carcinoma (1); Renal insufficiency (1); rheumatoid arthritis (1).
A further 5 diseases each share a sentence with SEC61A1 in 1 paper.